EGFR (epidermal growth factor receptor)
Diseases named in the same sentence as EGFR in open-access papers (continued):
Sharing a sentence is not in itself a finding about the gene and the disease.
breast tumors (continued). "Notably, expression of the CD81 interactor and HCV entry facilitator CBLB is altered in gastric and breast tumor tissue and CBLB regulates cell migration and epidermal to mesenchymal transition (EMT) through EGFR degradation." (PMID 30024968, 2018). "The percentages of positive expression for p-ER, EGFR, p-ERK1/2, p-mTOR and IGF1R were also in line with previous published data, using similar population selection, IHC methods, and assessment criteria in primary invasive breast tumors." (PMID 29486734, 2018). "One point of caution is, however, that EGFR is not very highly expressed in most breast tumour cells." (PMID 29941867, 2018). "Of note, recent studies demonstrated that macrophages isolated from human breast tumors could release epithelial growth factor (EGF), while MUC1 has been reported to enhance EGFR expression and involving in neoplasia and cell adhesion." (PMID 29423058, 2018). "To confirm the in vitro phenotype of the EGFR/miR-338-3p/EYA2 pathway, we first investigated the effect of the pathway on breast tumor growth by injecting 4T1 cells harboring the indicated constructs and/or the miR-338-3p inhibitor into the mammary fat pads of BALB/c mice." (PMID 28703807, 2017). "Since the overexpression of EGFR and PHD2 in a hypoxic environment may have a profound role in breast tumor progression and metastases, we hypothesized that there might be an association on a molecular level between PHD2 and EGFR." (PMID 28038470, 2017). "Basal human breast tumours also carried protein expression outliers in IDH1, EGFR and MAP2K1." (PMID 28348404, 2017). "Amongst the molecular markers tested, epidermal growth factor receptor (EGFR) expression was significantly associated with IKKε expression (p = 0.0011), as 72% of the IKKε− breast tumors were also negative for EGFR expression." (PMID 28532474, 2017). "To further determine whether AXL is involved in E1A-mediated EGFR-TKI sensitization in vivo, we performed an orthotopic breast tumor growth assay in an animal model." (PMID 27590506, 2016). "Similarly, radiosensitization by lapatinib, another small tyrosine kinase inhibitor targeting both EGFR and HER2, was shown to correlate with inhibition of phosphorylated AKT in breast tumor xenografts." (PMID 23874590, 2013). "About a third of breast tumours that are diagnosed as triple-negative overexpress the epidermal growth factor receptor (EGFR) and most of these tumours also show upregulation of the PI3K/AKT signalling pathway." (PMID 23441137, 2013). "In addition, ligands for the EGFR such as transforming growth factor-a, amphiregulin, epiregulin, betacellulin, and heparin-binding EGF stimulate the receptor in primary breast tumors to enhance local growth and progression of the disease." (PMID 18597688, 2008). "Studies on human breast tumor cells have shown that DHA and EPA could actually decrease membrane lipid raft EGFR protein level and mediate part of growth inhibitory effects of DHA on tumor cells." (PMID 19014610, 2008). "Given our previous results on WNT-induced EGFR transactivation, we considered it possible that WNT signaling might also play a role in some breast tumors." (PMID 17897439, 2007). "Most of the ER- breast tumors and cell lines over-expressed EGFR mRNA, and those that did not tended to over-expressed HER2." (PMID 17598908, 2007). "Epidermal growth factor receptor (EGFR) expression is mainly present in ERα-negative breast tumours and is a marker of poor prognosis." (PMID 15642172, 2005). "Since some types of breast tumors are hormone-sensitive, a potential mechanism of lignans may be due to ER binding, but also via inhibition and downregulation of HER2 (human epidermal growth factor receptor 2) and EGFR (epidermal growth factor receptor)." (PMID 36615537, 2023). "There is a negative correlation between VPS4B expression and EGFR stability in breast tumors." (PMID 37404768, 2023).
breast tumors (continued). "Furthermore, basal-like breast tumors have elevated expression of CK5, CK14, caveolin-1, caix, p63, and EGFR (epidermal growth factor receptor)/HER1; and the reduced expression of ER, PR, and HER2 impacts the basal/myoepithelial cell component of the mammary gland." (PMID 35629858, 2022). "Second, EGFR is not described as a universal oncogenic driver in breast tumours, suggesting that, at least in some tumours, aerotaxis may be dependent on other signals." (PMID 36380366, 2022). "Besides, in an allograft model, the effect of docetaxel in suppressing breast tumor growth was potentiated by the administration of MEL, and the programmed death ligand-1 (PD-L1) protein expression, phosphorylated HER2 and epidermal growth factor receptor (p-EGFR), were significantly reduced." (PMID 36238572, 2022). "Similarly, UNC5A and EGFR expression showed negative correlation in breast tumor samples when the analyses included all samples or only ER+ samples." (PMID 29720215, 2018). "(F) Staining of a patient-derived mouse xenograft breast tumor using the OMX Blaze with a 60x/1.42NA objective shows a spindle in a mitotic cell (beta-tubulin in red) as well as vesicles staining positive for VEGFR2 (in cyan) and punctuate expression of the EGFR in the plasma membrane (in green)." (PMID 29993362, 2018). "For instance, ligand-activated GPER triggers a network of transduction pathways such as EGFR, intracellular cyclic AMP, calcium mobilization, MAPK and PI3K, thus leading to the induction of genes involved in the proliferation, migration and invasion of cancer cells including breast tumor cells." (PMID 29290975, 2017). "The strongest single association detected in the present study was the one between the breast primary tumor EGFR expression and lung metastases, and as many as 75.8% of all those patients whose first distant recurrence was in the lung had either EGFR-positive or HER2-positive primary breast tumor." (PMID 21914172, 2011). "Furthermore, there are 7 literature support of genes MUC1 and HNF3-alpha related to breast neoplasm compared to 6 (MUC1) for EGFR and none for IKBKB." (PMID 18254968, 2008). "Interestingly, the expression levels of PTGS2 (-4.80-fold change) and EGFR (-2.45-fold change) regulated by hsa-mirR128, ABCB1 (-2.21-fold change), IGF1 (-2.19-fold change), and IL6 (-2.85-fold change) regulated by hsa-miR-223, were significantly reduced in breast tumour tissue." (PMID 32577155, 2020). "Thus, PKM2 may not contribute to such a breast tumor tumorigenesis and progression induced by Brca other than the EGFR signaling pathway." (PMID 30333907, 2018). "In summary, the present study demonstrates that EGFR/HER1 is suppressed and negatively associated with estradiol and ER, whereas HER3, and potentially HER2 and HER4, are elevated and positively associated with estradiol in HER2 non-amplified breast tumours from postmenopausal women." (PMID 23991224, 2013). "In addition, nearly all breast tumours having EGFR and/or ErbB2 overexpression were contained in the IBC-rich sample cluster: 17 out of 33 EGFR and/or ErbB2-positive samples in the IBC-rich cluster versus 25 out of 26 EGFR- and ErbB2-negative samples in the IBC-poor cluster (Pearson χ2, P<0.0001)." (PMID 17848951, 2007). "We found no strong evidence that p-ER, EGFR, p-ERK1/2, p-mTOR, or IGF1R are differently expressed in breast tumors of women with and without diabetes." (PMID 29486734, 2018). "Expression of Claudin-4, EGFR, CAIX, GLUT-1 and IGF1R was assessed by immunohistochemistry on tissue microarrays composed of 97 paired primary breast tumors and their distant (non-bone) metastases." (PMID 25417118, 2014).
breast tumors (continued). "Increased microvascular density has been correlated with active EGFR, tumor-type, tumor grade, and VEGF expression but not with HER2 expression in breast tumors." (PMID 18320059, 2008). "Thus, if cell lines are representative of the derivative disease, one would expect to see higher levels of EGFR and lower levels of ERBB3 and CDKN1B in non-breast indications vs. breast tumors." (PMID 27035903, 2016). "In addition, 5 out of 7 and 4 out of 7 basal-like tumours showed respectively EGFR and CK5/6 overexpression compared to only 3 out of 52 and 5 out of 52 in the non-basal-like breast tumours (Pearson χ2, respectively P<0.0001 and 0.001)." (PMID 17848951, 2007).
brain tumors (251 papers, 1992 to 2025). "Beyond the drug delivery, EGFR is an attractive biomarker also for brain tumor imaging, acting as both a diagnostic and therapeutic agent." (PMID 36839827, 2023). "Down-regulated DEGs in recGBM included genes involved in cell proliferation (EGFR), possibly brain tumor cell growth (BCAN), deadenylation of mRNA, which is linked to neurodevelopmental disorders (CNOT2), and multi-drug resistance (ABCG2)." (PMID 37189838, 2023). "Epidermal growth factor receptor (EGFR) is associated with a malignancy phenotype that is distinct from the low levels of brain tumors and has been found in more than 50% of GBMs36." (PMID 37179387, 2023). "It has been reported that e-liquid exposure can promote cell proliferation and malignancy of brain tumors by activating the epidermal growth factor receptor (EGFR) associated with cell growth." (PMID 35563421, 2022). "In a brain tumor, one of the most commonly studied changes in EGFR is EGFR transcript variant III (EGFRvIII), This mutation is due to a histone modification on its enhancer gene on chromosome 7p12." (PMID 34210107, 2021). "We observed lower incidences of KDD in ERBB2, ERBB3 and ERBB4 than EGFR, with distributions mirroring those of other observed oncogenic mutations in brain tumors and NSCLC13–17." (PMID 33654076, 2021). "In similarity to brain tumors, lung tumors displaying EGFR mutations frequently associate with EGFR gene amplification." (PMID 34206026, 2021). "We also noted those patients with EGFR mutation tended to be older and their brain tumor size tended to be smaller." (PMID 29447182, 2018). "Upregulation of the gene encoding EGFR is responsible for aberrant EGFR expression in 30% to 40% of primary brain tumors or brain tumor–derived cell lines." (PMID 29029486, 2017). "Many of these high grade and aggressive brain tumors were shown to release, or shed, EVs that contained a highly oncogenic form of the epidermal growth factor receptor (EGFR), called EGFR variant type III (EGFRvIII)." (PMID 27941677, 2016). "EGFR gene amplification is another biological factor potentially implicated in ECM of primary brain tumors." (PMID 26199775, 2015). "Epidermal growth factor receptor (EFGR, also known as ErbB1) overexpression has been strongly implicated in highly malignant brain tumors." (PMID 19936081, 2007). "Epidermal Growth Factor Receptor (EGFR) TK is often mutated in primary brain tumors, including GBM." (PMID 40564171, 2025). "The expression of epidermal growth factor receptor (EGFR) and its mutated form EGRRvIII has been reported in patients with a brain tumour, but none of their inhibitors has been approved for the treatment of patients with a brain tumour." (PMID 40227788, 2025). "Quantitative assessment of mRNA BDKRB1, PRKAR1A, MAP2K, and EGFR in patients with brain tumors may hold diagnostic and therapeutic significance." (PMID 38254732, 2024). "Down-regulated DEGs in recGBM were involved in cell proliferation (EGFR) and possibly brain tumor cell growth (BCAN), deadenylation of mRNA, which is linked to neurodevelopmental disorders (CNOT2), multi-drug resistance (ABCG2), and immune-related processes (GZMK)." (PMID 37189838, 2023). "Interestingly, the role of ARF6 was shown to be specifically involved in sorting and trafficking of EGFR toward degradation, while in aggressiveness in brain tumour-derived sEVs, Annexin1 is involved in inward budding EGFR-associated MVB." (PMID 37296932, 2023).
brain tumors (continued). "For example, the EGFR variant (rs149840192) that was found in the ccfDNA of patient 64 was registered in 36 brain tumor cases in the COSMIC database and was confirmed as somatic in one patient from our previous study and in three patients from the current study." (PMID 36010895, 2022). "In addition, EGFR TKIs combined with brain surgery or radiotherapy to treat metastatic brain tumors is still a popular strategy for patients with EGFR mutations and brain metastasis." (PMID 36612183, 2022). "Future studies using brain tumor tissues might provide a better understanding of the role of T790M mutation in patients developing BM during EGFR-TKI therapy." (PMID 29789021, 2018). "HIP1 physically associates with EGFR and maintains its levels in brain tumors." (PMID 25050814, 2014). "It will be important to test whether hypermethylation of these genes is related to other alterations such as IDH1 mutations and EGFR amplification found in brain tumors, Further studies will help clarify the usefulness of these alterations for detecting and managing patients with poor prognosis." (PMID 25621889, 2015). "In particular, EGFR-targeted antibody–drug conjugates (ADCs) for brain tumor therapy are under extensive development." (PMID 39598559, 2024). "Several combinations of target antigens have been proposed, such as EGFRvIII and IL-13Rα2, and EGFRvIII and EGFR, with the main objective of offsetting immune escape in brain tumors." (PMID 39199683, 2024). "According to Vouri’s study, AXL can amplify EGFR signaling by interacting with EGFR in brain tumor cells." (PMID 38338651, 2024). "In a study, CQDs based tumor detection probes were combined with aspartic acid to target brain tumors and observe the expression of epidermal growth factor receptor (EGFR) in human brain tumor cells." (PMID 39205871, 2024). "We chose the epidermal growth factor receptor (EGFR), a transmembrane protein often overexpressed in brain tumors, as the target antigen." (PMID 39598559, 2024). "We summarize the mechanisms underlying autophagy dysregulation in GBM, including PI3K/AKT/mTOR signaling, which is most active in brain tumors, and EGFR and mutant EGFRvIII." (PMID 39195222, 2024). "Single-cell gene expression data also pointed to human EGFR transcripts being detectable in endothelial cells of both human brain tumours and murine brain xenografts." (PMID 38570528, 2024). "For instance, MYC and EGFR have been reported to be critical for maintenance of the brain tumor-initiating cells in adult glioblastoma." (PMID 39419964, 2024). "H&E staining confirmed the presence of brain tumors and immunofluorescence staining with anti-EGFR, anti-DR4, and anti-DR5 antibodies confirmed the expression of the receptors specifically in the neoplastic space." (PMID 37311043, 2023). "Epithelial growth factor receptor (EGFR) is an interesting targetable candidate in advanced precision medicine for brain tumor patients." (PMID 37444635, 2023). "Here, we report the best-studied and promising receptors for brain tumor delivery, including the epidermal growth factor receptor (EGFR), transferrin receptor (TfR), insulin receptor (IGFR) and lipoproteins." (PMID 36839827, 2023). "This immunotoxin (TP) comprising TGFα and a modified Pseudomonas exotoxin A (PE38) derived from Pseudomonas aeruginosa was developed for the treatment of EGFR-expressing malignant tumors such as brain tumors." (PMID 36900277, 2023). "For example, immunoliposomes carrying anti-epidermal growth factor receptor (anti-EGFR) antibodies can enhance the ability of vinorelbine and doxorubicin to target brain tumor cells." (PMID 37108814, 2023). "Most brain tumors overexpress the epidermal growth factor receptor (EGFR), which can be targeted by cetuximab (CET), an EGFR monoclonal antibody, for drug delivery to GBM patients." (PMID 37629816, 2023).